TACR1 (tachykinin receptor 1)
Diseases named in the same sentence as TACR1 in open-access papers (continued):
Sharing a sentence is not in itself a finding about the gene and the disease.
psoriasis (5 papers, 2013 to 2025). An autoimmune condition characterized by red, well-delineated plaques with silvery scales that are usually on the extensor surfaces and scalp. "Meanwhile, this was the case for 16 of the itch-associated genes in MCs isolated from psoriasis skin, including CTSB, TLR4, and TACR1 (training set AUC OOB = 1, OOB Error rate = 11.11%, validation set AUC = 0.875, 95% CI = 0.63–1)." (PMID 37681909, 2023). "According to our findings, MCs derived from psoriasis lesions express higher levels of genes involved in the regulation of neurons, and in particular, receptors that could facilitate communication with sensory nerves, such as the substance P receptor (TACR1)." (PMID 37681909, 2023). "While these findings could indicate a prominent role of TACR1 in MC-dependent itch in psoriasis, we cannot exclude the contribution of the MRGPRX2-induced signalling pathway, as this receptor is known to be constitutively and preferentially highly expressed in skin MCs." (PMID 37681909, 2023). "In our study, TACR1 was upregulated in psoriasis MCs, while MRGPRX2 displayed no significant changes in its expression." (PMID 37681909, 2023). "Furthermore, the inflammatory indicators found to be upregulated in psoriasis MCs, such as ATF4, CXCL12, LTA, TACR1, TLR4, and CTSB, interestingly share IL-1β as a common modulator." (PMID 37681909, 2023).
colorectal cancer (4 papers, 2020 to 2022). A primary or metastatic malignant neoplasm that affects the colon or rectum. "In studies of other cancers, researchers found that TACR1 correlates with the prognosis of colorectal cancer (CRC) and gastric cancer (GC)." (PMID 35903353, 2022).
osteoporosis (4 papers, 2020 to 2023). A condition of reduced bone mass, with decreased cortical thickness and a decrease in the number and size of the trabeculae of cancellous bone (but normal chemical composition), resulting in increased fracture incidence. "The neuropeptide VIPR1, finally, promotes bone mineralization, while TACR1 regulates the osteoblasts, osteoclasts and mesenchymal stem cell functionality associated with protection from osteoporosis." (PMID 32927845, 2020).
preeclampsia (3 papers, 2020 to 2024). Preeclampsia is a hypertensive disorder of pregnancy that is characterized by new-onset hypertension with proteinuria presenting after 20 weeks of gestation, and depending on mild or severe forms may initially present with severe headache, visual disturbances, and hyperreflexia. "Some genes are noted to play key roles in preeclampsia, including LPAR4/5, CRLR, NPY, TACR1/2, and SFRP4/5, whose functions generally relate to angiogenesis and vasodilation or vasoconstriction." (PMID 35269385, 2022).
tendinopathy (3 papers, 2017 to 2022). "In addition to inflammatory markers, neuroinflammation was investigated in the present study, as substance P and its receptor tachykinin receptor 1 are involved in tenocyte proliferation, angiogenesis, and pain, all of which are features of tendinopathy." (PMID 35008516, 2021).
hepatocellular carcinoma (2 papers, 2022). A malignant tumor that arises from hepatocytes. "LncRNA RMRP inhibition represses malignant progression of hepatocellular carcinoma by regulating miRNA-206/TACR1 signaling." (PMID 35132320, 2022).
mental disorder (2 papers, 2017 to 2018). A disease that has its basis in the disruption of mental process. "Despite using a small cohort, our study identified TACR1, a member of the tachykinin family that has previously been associated with other psychiatric disorders, dysregulated in AN." (PMID 28291261, 2017). "Although TACR1 has previously been associated with psychiatric disorders, we believe this is the first report of its contribution to AN." (PMID 28291261, 2017).
Nausea (2 papers, 2025). A sensation of unease in the stomach together with an urge to vomit. "This indicates that AA carriers of CHRM3 rs2165870 exhibited a preventive effect of ondansetron against nausea, whereas CC carriers of TACR1 rs3755468 exhibited only a limited preventive effect of ondansetron against nausea." (PMID 40691854, 2025). "Thus, TACR1 neurons in the CNS could play a central role in TACR1-related nausea." (PMID 40691854, 2025). "CHRM3, whose-related nausea responded to ondansetron, is expressed at higher levels in the upper gastrointestinal tract compared to TACR1, whose-related nausea did not respond to ondansetron, consistent with the access of ondansetron on CHRM3 in the upper gastrointestinal tract outside the BBB." (PMID 40691854, 2025).
anorexia nervosa (1 paper, 2020). A disorder most often seen in adolescent females characterized by a refusal to maintain a minimally normal body weight, an intense fear of gaining weight, a disturbance in body image, and, in postmenarcheal females, the development of amenorrhea. "In relation to the other anorexia nervosa associated genes, TACR1 expression ranks 56th of 342 in the adult lateral parabrachial nucleus." (PMID 32651428, 2020).
anxiety disorder (1 paper, 2017). A category of psychiatric disorders which are characterized by anxious feelings or fear often accompanied by physical symptoms associated with anxiety. "Although TACR1 has been associated with psychiatric conditions, especially anxiety disorders, we believe this report is its first association with AN." (PMID 28291261, 2017).
chronic sinusitis (1 paper, 2018). "Among the top associations is the gene TACR1 associated with chronic sinusitis (ICD-9 473.9; P-value = 2.01e − 10; beta = 2.34; functional annotation filter 3)." (PMID 29545597, 2018). "Other G-protein receptors such as IKACH, GNB2 are linked to some other forms of sinusitis but this association between functional annotation mutations in TACR1 and chronic sinusitis is novel." (PMID 29545597, 2018). "This novel association among functionally annotated mutations in TACR1 and chronic sinusitis warrants further investigation to understand what impact this drug may have in relation to sinusitis, including a potential side effect of tachykinin receptor blocking through the use of this drug." (PMID 29545597, 2018).
endothelial dysfunction (1 paper, 2025). In vascular diseases, endothelial dysfunction is a systemic pathological state of the endothelium (the inner lining of blood vessels) and can be broadly defined as an imbalance between vasodilating and vasoconstricting substances produced by (or acting on) the endothelium. "Recently, we reported endothelial dysfunction in GDM fetoplacental vessels characterized by reduced vasorelaxation in response to substance P. In addition, our recent study revealed a decrease in the mRNA expression of tachykinin receptor 1 (TACR1), the receptor for substance P." (PMID 41373661, 2025).
gestational diabetes (1 paper, 2025). Carbohydrate intolerance first diagnosed during pregnancy. "Finally, we found a significantly decreased substance P receptor (TACR1) mRNA expression in fetal vessel segments from patients with insulin-treated gestational diabetes." (PMID 39384641, 2025).
Headache (1 paper, 2025). Cephalgia, or pain sensed in various parts of the head, not confined to the area of distribution of any nerve. "CRISPR-based gene-editing strategies targeting pain-modulating genes, such as TACR1, have demonstrated potential in preclinical models for refractory headache management." (PMID 41181417, 2025).
meningoencephalitis (1 paper, 2018). Inflammation of the meninges and brain, generally secondary to an infectious cause. "However, in a mouse model of meningoencephalitis, the effects of combined treatment with NK2 and NK3 receptor antagonists were reduced on the neuroinflammatory scores in Tacr1−/− mice compared with similarly treated Tacr1+/+ mice." (PMID 29459872, 2018).
Telangiectasia (1 paper, 2023). Telangiectasias refer to small dilated blood vessels located near the surface of the skin or mucous membranes, measuring between 0.5 and 1 millimeter in diameter. "Significant expression changes existed also for genes responsible for the pathogenesis of telangiectasia (upregulation of Sst, Sstr1, Sstr2, Tac1, Tacr1, Svbp), and for general growth (Sst, Sstr1, Sstr2)." (PMID 37830614, 2023).
Tinnitus (1 paper, 2025). Tinnitus is an auditory perception that can be described as the experience of sound, in the ear or in the head, in the absence of external acoustic stimulation. "The interactions of TACR1 and TACR3 in the motor system of the thalamus appear to have an inhibitory effect under the conditions of tinnitus, thereby attenuating, inhibiting, or normalizing the influence of tinnitus signals that are perceived in the AuS." (PMID 40565265, 2025).
tumor (70 papers, 1999 to 2026). "Precisely, GSE micro array data shows tendencies towards a decreasing expression of total TACR1 with tumor stage progression, while TAC1 tends to increase with higher stages." (PMID 34070805, 2021). "Significant decline of TACR1 in PDAC tumor tissues in the course of tumor progression is in line with survival curves demonstrating lower expression of TACR1 to correlate with poorer survival." (PMID 34070805, 2021). "The comparison of the PDAC data sets obtained from Gene Expression Omnibus (GEO), the Cancer Genome Atlas (TCGA), and Cancer Cell Line Encyclopedia (CCLE) allowed identification of a significant downregulation of TACR1 in tumor vs. normal cells." (PMID 34070805, 2021). "TACR1 is expressed in the peripheral and central nervous systems and is indispensable to the maintenance of a favorable tumor microenvironment." (PMID 26251921, 2015). "For the first time, we present the expression of TACR1 and TAC1 in rhabdoid tumors, the potent inhibitory effect of the NK1R antagonist aprepitant in this tumor entity and the analysis of apoptotic pathways of rhabdoid tumor cells upon treatment with aprepitant." (PMID 35049682, 2021). "TACR1-fl expression was found to be very low in all tumor samples analyzed." (PMID 35049682, 2021). "Although TACR1 signaling pathway status in HNSCC is unclear, this TACR1-induced Nur77 pathway might contribute to the proposed role of TACR1 as a tumor suppressor in HNSCC." (PMID 26251921, 2015). "NK1R (Tachykinin Receptor 1) activates the AURKA/MYCN signaling pathway through PKCα and its knockdown results in the reduction of tumor burden and suppression of NE features in vivo." (PMID 37761978, 2023). "Varying expression of TACR1-tr and TAC1 release is in line with the TCGA data, where we found trends related to tumor stages." (PMID 34070805, 2021). "Expression levels of TACR1-tr were found the highest in an RT of the liver tumor tissue sample (T125II), and the lowest in AT/RT tumor tissue samples (T16, T12IC)." (PMID 35049682, 2021). "Data mining in publicly available datasets, such as TCGA, GEO, and CCLE, with additional consideration of OncoLnc survival data, allowed for linkage of differential expression of TACR1 and TAC1 to tumor progression and EMT state of cancer cells." (PMID 34070805, 2021). "SSTR1 hypermethylation in 64% of cases was correlated with tumor size (P = 0.037), stage (P = 0.037), SST methylation (P < 0.001), and expression of galanin (P = 0.03), GALR2 (P = 0.014), TAC1 (P = 0.023), and tachykinin receptor type 1 (TACR1) (P = 0.003)." (PMID 25734919, 2015). "The expression levels for the TACR1 gene were compared between nontumor cells such as normal human fibroblasts and normal kidney epithelial cells, HEK293, and the osteosarcoma tumor cell line, MG-63." (PMID 36983138, 2023). "Overall, we observed that TACR1 and TAC1 were expressed across different tumor stages and independent of gender or age of diagnosis." (PMID 35049682, 2021). "Putative GPR15 co-expressed genes, such as TACR1, TAS2R9, SPDYE4, or GPR182, could be a more specific sign for tumor cells of adenocarcinoma or for healthy epithelial cells from which the tumor originates since all four genes were not expressed in GPR15+CD3+ lymphocytes." (PMID 34639163, 2021).
cancer (69 papers, 2007 to 2025). A tumor composed of atypical neoplastic, often pleomorphic cells that invade other tissues. "The TACR1 gene, encoding a receptor linked to various cancers, also showed decreased expression, highlighting TQ’s potential in cancer cell apoptosis." (PMID 39874307, 2025). "Substance P interacts with the tachykinin receptor TACR1 on tumor cells, resulting in the demise of a specific subset of cancer cells that exhibit high TACR1 expression." (PMID 40092993, 2025). "Our results suggest that determining the genotype of these polymorphisms except for TACR1 and HTR3B can help to inform individually based medication for treating or preventing CINV using genomic information for the Japanese cancer patients." (PMID 27446594, 2016). "TACR1 activation by substance P has been reported to be mitogenic in cancer cell lines." (PMID 27888795, 2017). "Interestingly, cancer cells expressing higher levels of the truncated tachykinin receptor 1 (TACR1) isoform exhibit more important sensitivity to NK-1R inhibition which might enable the stratification of PDAC patients who could benefit from NK-1R-targeted therapies." (PMID 39766161, 2024).
infection (17 papers, 2008 to 2025). The state of being infected such as from the introduction of a foreign agent such as serum, vaccine, antigenic substance or organism. "Together these data demonstrate that TACR1 signaling is a critical element of host responses during enteric bacterial infection and blocking TACR1 signaling reduces bacterial burden and infection-induced pathology." (PMID 39937862, 2025). "Using potent and selective TACR1 antagonists, we demonstrate significantly reduced C. rodentium burden, and infection-induced colonic pathology." (PMID 39937862, 2025). "With the reduced IFNγ production by TACR1 T cell cKO compared to WT mice during infection, we assessed whether T cells from these mice were able to proliferate and differentiate to Th1 or Th17 T cells." (PMID 39937862, 2025). "In support of SP receptor regulation of specific gene expression profiles in response to enteric bacterial infection, Tnfa and Il1β expression induced by infection were significantly reduced by TACR1 antagonism 29 dpi compared to vehicle-treated and infected mice." (PMID 39937862, 2025).
TACR1 also shares sentences with these, for which no sentence is quoted: depression (28 papers); glioma (17); asthma (13); colitis (13); pancreatic cancer (11); astrocytoma (6); attention deficit-hyperactivity disorder (6); diabetes (6); neuropathy (6); pancreatitis (6); retinoblastoma (6); Stroke (6); acute lymphoblastic leukemia (5); acute myeloid leukemia (5); Arthritis (5); inflammation (5); injury (5); leukemia (5); Parkinson disease (5); rheumatoid arthritis (5); bacterial infections (4); esophageal squamous cell carcinoma (4); gallbladder cancer (4); head and neck cancer (4); liver fibrosis (4); migraine (4); neurodegenerative disease (4); oral cancer (4); adenomyosis (3); alcoholism (3).
A further 154 diseases each share a sentence with TACR1 in 3 papers or fewer.